MIR433 (microRNA 433)
Synonyms: hsa-mir-433; MIRN433; miRNA433; mir-433
Gene: MicroRNA gene on chromosome 14 (100,881,886 to 100,881,978, forward strand). Ensembl gene ENSG00000207569.
Gene Ontology:
Biological process: cellular response to leukemia inhibitory factor; cellular response to lipopolysaccharide; long-term synaptic potentiation; miRNA-mediated post-transcriptional gene silencing
Cellular component: RISC complex
Homologues: Orthologues: chimpanzee ptr-mir-433 (100% identical), guinea pig MIR433 (100% identical), mouse Mir433 (100% identical), rat Mir433 (100% identical), macaque mml-mir-433 (99% identical), rabbit MIR433 (76% identical).
Diseases named in the same sentence as MIR433 in open-access papers:
MIR433 is named in the same sentence as 1 disease in open-access papers, as found by Europe PMC text mining. Sharing a sentence is not in itself a finding about the gene and the disease. The quoted sentences say what the papers report.
tumor (1 paper, 2021). "One study reported that MIR433 down-regulation is connected to tumor suppression, which was in agreement with our study, whereas another mentions that MIR433 up-regulation has tumor suppressive effects." (PMID 34204289, 2021).